BRCA1 (BRCA1 DNA repair associated)
Diseases named in the same sentence as BRCA1 in open-access papers (continued):
Sharing a sentence is not in itself a finding about the gene and the disease.
ovarian carcinoma (continued). "The study of BRCA1 and BRCA2 genes and their alterations has been essential to the understanding of the development of familial breast and ovarian cancers." (PMID 25683334, 2015). "We selected female BRCA1 mutation carriers having had a diagnosis of breast or ovarian cancer below 40 years of age (young cancer group, N = 40), and mutation carriers having had neither breast nor ovarian cancer above 60 years of age (i.e., old no cancer group, N = 38)." (PMID 26052370, 2015). "17-AAG downregulated protein levels of BRCA1 and RAD51 in 36M2 and RAD51 alone in SKOV3 ovarian cancer cell lines." (PMID 24798692, 2014). "We review the molecular signaling pathways that converge on BRCA1 and BRCA2, their activation status in ovarian cancer, and therapeutic options to modulate BRCA function." (PMID 24624361, 2014). "In agreement with recent findings in other tumors such as epithelial ovarian cancer (EOC), gastric, nasopharyngeal carcinoma, we also found a relationship between BRCA1 expression and different times of survival in our cohort." (PMID 25594033, 2014). "Furthermore, it has been suggested that a subset of sporadic ovarian cancer, in the absence of BRCA1/2 mutation, may harbor HR deficiency and stand to benefit from platinum compounds and PARP inhibitor." (PMID 25437005, 2014). "Promoter hypermethylation of at least one of six genes (BRCA1, RASSF1A, APC, p14ARF, p16INK4A and DAPK) was observed in 41/50 ovarian cancer serum specimens." (PMID 24821107, 2014). "The inactivation of BRCA1 or BRCA2 (BRCA1/2) is considered to be an important step in the tumorigenesis of breast and ovarian cancers." (PMID 25158060, 2014). "The model’s ability to distinguish between BRCA1/2 mutation carriers and non-carriers might, in the context of a positive family history of breast and/or ovarian cancer, serve as an indicator to consider formal genetic risk assessment in persons who have not been previously tested." (PMID 25159706, 2014). "The inhibition of H2O2 generation was also confirmed in an isogenic ovarian cancer cell model UWB1.289, which lacks a wild type BRCA1 gene and UWB1.289+BRCA1, which expresses wild type BRCA1 by stable transfection." (PMID 24704793, 2014). "Thus, the score may also predict outcome of a large number of ovarian cancer patients, regardless of BRCA1/2 mutation status." (PMID 25437005, 2014). "Our unpublished data show that Dinaciclib exposure results in downregulation of BRCA1 and BRCA2 and sensitized cyclin E1-dependent ovarian cancer cells to cisplatin." (PMID 24624361, 2014). "Introduction of Aur A and/or B shRNAs into cells along with BRCA1 or/and BRCA2 shRNAs in both pancreatic and ovarian cancer cells evidently reduced the number of colonies, compared with in cells expressing BRCA1 or/and BRCA2 shRNAs only." (PMID 24775809, 2014). "Compared to stage I and healthy subjects, there were higher BRCA1 promoter methylation frequencies in stage II and III ovarian cancers." (PMID 24821107, 2014). "Because of the rapidly evolving nature of BRCA1, we also completed an evolutionary analysis of BRCA2, another strong determinant for hereditary breast and ovarian cancer." (PMID 25011685, 2014). "Furthermore, 45.8% of breast/ovarian cancer patients with inherited BRCA1 and BRCA2 mutations do not have a clear family history due to a small family structure, predominance of males in the family and/or paternal inheritance, adoption or non-biological father." (PMID 23536787, 2013). "Poly(ADP-ribose) polymerase (PARP) inhibitors, which are especially effective in cancer associated with BRCA1 or BRCA2 mutation, have shown considerable promise in triple-negative breast cancer and may be valuable in treating high-grade serous Type II ovarian cancer." (PMID 23536770, 2013). "The DNA repair genes BRCA1, MLH1, and MGMT were among those genes affected by hypermethylation in ovarian cancer." (PMID 23344037, 2013).
ovarian carcinoma (continued). "BRCA1 protein immunohistological staining with the MS110 antibody has shown a speckled nuclear pattern in many breast and ovarian cancer cell lines, as well as in centrosomes and mitochondria." (PMID 23855721, 2013). "Thus the mechanisms by which BRCA1 suppresses breast and ovarian cancer development may differ." (PMID 23802008, 2013). "As both predictive and prognostic marker, low BRCA1 protein expression correlated with better clinical outcome in terms of both PFS and OS in patients with epithelial ovarian cancer treated with platinum." (PMID 23326344, 2013). "Both BRCA1 and epidermal growth factor receptor (EGFR) play a critical role in ovarian cancer progression." (PMID 24321281, 2013). "Moreover, multiple genetic and epigenetic mechanisms cause the inactivation of BRCA1, BRCA2, and/or other repair factors in hereditary and sporadic ovarian cancer, and it was estimated that as much as 50% of epithelial ovarian cancer could be homologous recombination deficient." (PMID 23344037, 2013). "These new high throughput testing methodologies, can detect multiple ovarian cancer biomarkers including focal amplifications of the HER2 and CCNE1 oncogenes, and somatic deletions of the BRCA1, BRCA2 genes in a single test." (PMID 23289505, 2013). "We also carried out MLPA analysis in 132 index cases from BRCA1/BRCA2-negative families with breast and/or ovarian cancer with either a personal or familial history of pancreatic cancer." (PMID 23935836, 2013). "Additionally, an ovarian cancer patient who was negative for the highly -penetrant BRCA1 variant was found to carry a heterozygous form of the 2q34 deletion, suggesting that the deletion may also contribute to ovarian cancer risk to some extent." (PMID 23967248, 2013). "Taken together, BRCA1 and BRCA2 appear to play critical roles in development of ovarian cancer and modulation of chemotherapy responsiveness." (PMID 23964347, 2013). "Of particular interest and potential clinical relevance, the relationship between BRCA1 and AGTR1 expression was studied in 63 human ovarian cancer specimens." (PMID 24321324, 2013). "Both BRCA1 and angiotensin II type 1 receptor (AGTR1) play a critical role in ovarian cancer progression." (PMID 24321324, 2013). "If larger studies confirm our findings, TNBC therefore may be included within clinical criteria for BRCA1 and BRCA2 mutation screening, and additional cases may be assessed not only if they present with early-onset of the disease or have a familial aggregation of breast and/or ovarian cancer." (PMID 22666503, 2012). "Thus, it has been hypothesized that mutations of other functional partners in the BRCA pathway could account for a subset of breast and ovarian cancers lacking BRCA1 and BRCA2 mutations." (PMID 22792303, 2012). "The role of BRCA1 and BRCA2 in the pathogenesis of breast and ovarian cancer in Pakistan was noted, and the most prevalent Pakistani mutations were highlighted." (PMID 21559243, 2011). "In primary ovarian carcinomas, ZEB1 binding site methylation and TAp73 expression correlated with BRCA1 status and with clinical response." (PMID 24212667, 2011). "To examine whether genetic variants in miRNA genes might be able to explain some of the unidentified genetic predisposition in familial ovarian cancer, we screened genetic variants in select miRNA genes in ovarian cancer patients who are non-carriers of any known BRCA1/2 or MMR gene mutations." (PMID 20167074, 2010). "An overlapping set of seven genes (ABCB1, APC, BRCA1, CDH1, DNAJC15, HIC1 and SULF2) displayed the same methylation changes in the examined set of ovarian carcinoma cell lines." (PMID 20544021, 2010). "An ovarian cancer cell line SKOV3, which expresses high levels of BRCA1, was the model used to assess the role of BRCA1 in cisplatin sensitivity." (PMID 20182637, 2010). "In sporadic epithelial ovarian cancer (EOC), the inactivation of BRCA1 through various mechanisms is a relatively common event." (PMID 20182637, 2010).
ovarian carcinoma (continued). "Promoter methylation leads to decreased expression of BRCA1, MLH1, and FANCF protein in a subset of ovarian carcinomas." (PMID 19602291, 2009). "We evaluated BRCA1, BRCA2, and MLH1 protein expression in 115 sporadic primary ovarian carcinomas, of which 31 had paired recurrent neoplasms collected after chemotherapy." (PMID 19602291, 2009). "MLH1, BRCA1, and BRCA2 protein expression was also assessed in 31 matched primary and recurrent ovarian carcinomas from the same patient to determine if chemotherapy influenced MLH1, BRCA1, or BRCA2 protein levels." (PMID 19602291, 2009). "Our data demonstrate that BRCA1 and BRCA2 protein expression are highly concordant in ovarian carcinomas." (PMID 19602291, 2009). "As part of the model-fitting process, we also estimated the BRCA1 and BRCA2 breast and ovarian cancer risks, but these were based on a relatively small number of mutation-carrying families and were therefore imprecise." (PMID 18349832, 2008). "This is the first study to comprehensively examine data from detailed analysis of BRCA1 and BRCA2 abnormalities in ovarian cancer." (PMID 18208621, 2008). "It is known that the risk for ovarian cancer might vary depending on the location of the mutation within the BRCA1/2 coding sequence although this information is generally not used in the counselling process and does not appear in any national guidelines broadly used." (PMID 18783588, 2008). "BRCA1 and BRCA2 proteins are thought to be essential to prevent breast/ovarian cancer largely because of the high lifetime risks faced by carriers of mutations in the corresponding genes." (PMID 17683622, 2007). "At the first screening visit, five women (four BRCA1 and one BRCA2) were diagnosed with a prevalent ovarian cancer." (PMID 17426707, 2007). "Incidence for BRCA1, p14, p16 and PTEN in ovarian cancer was 24.5%, 18.4%, 16.3% and 8.2% respectively." (PMID 16928264, 2006). "Four loci including DAPK, MGMT, p16 and PTEN were selected for methylation analysis in 127 cervical cancers; APC, CDH13, p16 and hMLH1 were examined in 60 endometrial cancers; and BRCA1, p14, p16 and PTEN in 49 ovarian cancers." (PMID 16928264, 2006). "The same table shows the predicted contributions of BRCA1 and BRCA2 to cases diagnosed with ovarian cancer." (PMID 15381934, 2004). "The ovarian cancer incidence rates in BRCA1 carriers rise to a peak in the 40–49 years age group, followed by a slight decline, while the BRCA2 ovarian cancer incidence rates were highest in the 50–59 year age group." (PMID 11857015, 2002). "BRCA1 and BRCA2 have been reported to be factors influencing survival in ovarian cancers." (PMID 41614943, 2026). "Somatic mutation and copy-number data from >3000 breast and ovarian cancers in TCGA and METABRIC were compared between germline BRCA1/2 carriers and non-carriers matched on subtypes." (PMID 41724111, 2026). "Thus, BRCA1/BRCA2’s strong tumor-suppressive effects appear largely confined to hereditary breast and ovarian cancer." (PMID 40841483, 2026). "By contrast and as observed in ovarian cancer, a subset of patients derived clinical benefit of this combination irrespective of BRCA1/2-gene or PD-L1 status, again stressing the need to identify specific biomarkers of response for such combinations." (PMID 41188872, 2025). "Additionally, DDSR1 supports BRCA1 recruitment during HR61, while targeting NEAT1 sensitices ovarian cancer cells to PARPi by regulating RAD5162." (PMID 41034557, 2025). "Noncarriers had elevated CBC and nonbreast/ovarian cancer SIRs, which were lower than the corresponding BRCA1-or BRCA2-specific SIRs (CBC: SIR, 3.03 [95% CI, 2.67 to 3.43]; nonbreast/ovarian: SIR, 1.26 [95% CI, 1.14 to 1.38])." (PMID 39475295, 2025). "BRCA1/BRCA2 PV carriers had elevated combined nonbreast/ovarian cancer SIRs (BRCA1: SIR, 2.18 [95% CI, 1.59 to 2.92]; BRCA2: SIR, 1.68 [95% CI, 1.24 to 2.23])." (PMID 39475295, 2025).
ovarian carcinoma (continued). "Elevated chromosome instability scores were observed in BRCA1-mutated samples over non-BRCA HRR-related mutations (P < 0.001), with BRCA2-mutated ovarian cancer exhibiting greater chromosome instability scores (P < 0.01)." (PMID 40687614, 2025). "Accordingly, current American Society of Clinical Oncology guidelines recommend BRCA1/2 sequencing for all ovarian cancer patients, irrespective of histologic subtype." (PMID 41425725, 2025). "Three of the four PARPi used to validate the competitive growth assay are FDA approved for the treatment of BRCA1/2 negative breast and/or ovarian cancers (olaparib, niraparib and talazoparib)." (PMID 40982437, 2025). "In a patient affected with ovarian cancer, tumor genomic profiling did not identify the P/LPGVS in BRCA1; the variant was identified on germline testing." (PMID 41465149, 2025). "Thus, we added DAPK1, a new gene, to the list of hypermethylated tumor suppressors, including BRCA1 and RASSF1A, that are prognosis-relevant in ovarian cancer." (PMID 40563561, 2025). "The mean scores of the BRCA1/2-negative groups (16.1 for Group 2 and 12.8 for Group 5) were also similar to those from the original report on the MICRA (12.7–15.1) and a previous study of patients with ovarian cancer (14.9–17.1)." (PMID 40900191, 2025). "Most missense variants in the BRCA1, BRCA2, and ATM genes do not confer an increased risk of breast and ovarian cancer, but ones in specific domains do." (PMID 39858629, 2025). "For instance, women who carry BRCA1 and BRCA2 gene mutations are at high risk of various cancers (e.g., breast, pancreas, and ovarian cancers) —but not everyone who inherits these mutations will develop cancer." (PMID 40832617, 2025). "While their role in OSCC is not as well-defined as in breast and ovarian cancers, emerging evidence suggests that BRCA1 and BRCA2 contribute to tumor initiation, progression, and therapeutic resistance." (PMID 40224184, 2025). "A 37-year-old premenopausal woman, with no family history of breast or ovarian cancer, and confirmed germline BRCA1 and BRCA2 wild-type, was referred to our institution following a left breast tumorectomy performed at another hospital." (PMID 41018107, 2025). "Unlike BRCA1/2, PVs in ATM and CHEK2 do not confer sufficient ovarian cancer risk to warrant recommendation of risk-reducing salpingo-oophorectomy." (PMID 40298171, 2025). "Women with BRCA1/2 PVs without a history of breast and/or ovarian cancer were recruited in six centres across Germany." (PMID 39875875, 2025). "The most notable example so far is the use of PARP inhibitors (PARPi) to treat individuals with inherited breast and ovarian cancers lacking wild-type copies of the BRCA1 and BRCA2 genes." (PMID 39987121, 2025). "The associations of age at ovarian cancer diagnosis and histology between BARD1 mutation carriers and BRCA1/2 mutation carriers were not calculated due to limited case numbers." (PMID 40805222, 2025). "HRD scores were comparable between BRCA1-and BRCA2-mutated ovarian cancer but significantly higher than in patients with non-BRCA HRR-related pathogenic mutations (P < 0.001) or wild-type HRR-related genes (P < 0.001)." (PMID 40687614, 2025). "Ten-year cumulative CBC, ovarian, and combined nonbreast/ovarian cancer risks were 16%/6.3%/7.8% (BRCA1 carriers), 12%/3.0%/6.2% (BRCA2 carriers), and 3.6%/0.4%/4.9% (noncarriers)." (PMID 39475295, 2025). "In November 2020, niraparib was registered in Europe—a new and only maintenance monotherapy after first-line chemotherapy for patients with advanced ovarian cancer, regardless of the BRCA1/2 status." (PMID 40002896, 2025). "Several mechanisms of PARPi resistance have been identified in vitro (e.g. cancer cell lines and patient-derived organoids) and in vivo (clinical samples) with significant differences based on genetic background (e.g. BRCA1 vs. BRCA2 mutant) and tumor types (e.g. breast vs. ovarian cancer)." (PMID 39927794, 2025).
ovarian carcinoma (continued). "In view of the influence of HRT on the risk of breast and ovarian cancer in the general population, an increase in risk following HRT for BRCA1/2-pV carriers cannot be ruled out based on the current data." (PMID 39259360, 2024). "However, BRCA1 and RAD51C promoter hypermethylation have been reported only in sporadic breast and ovarian cancer cases." (PMID 39406235, 2024). "In this study, we assessed the predictive potential of the BRCA1 foci test, similar to the RAD51 foci assay, in a large collection of 55 well-characterized ovarian carcinoma patient-derived xenograft (OC-PDX) models, whose response to cisplatin (DDP) and olaparib, a PARPi, is known." (PMID 38989145, 2024). "Additionally, we aimed to determine the roles of constitutional BRCA1 promoter methylation and MGMT promoter methylation in the incidence of ovarian cancer in Saudi women." (PMID 38542081, 2024). "Similarly, further studies have discovered that BRCA1 level was a prognostic biomarker of poor survival in some solid tumors patients, including NSCLC, ovarian cancer, hepatocellular carcinoma, uterine serous carcinoma, and nasopharyngeal carcinoma." (PMID 38224491, 2024). "USP1 dependency has been related to the aberrant processing of mono- and poly-Ub PCNA in BRCA1/2 mutant tumors as well as in BRCA1/2 wild-type cell lines including ovarian cancer cells." (PMID 39430244, 2024). "Pharmacologic inhibition of PARP is the primary therapeutic strategy for BReast CAncer gene (BRCA) mutant ovarian cancer, but most patients carry wild-type BRCA1/2 and show no clinical benefits from PARP inhibitors." (PMID 38203758, 2024). "As the PoC endpoint is neither breast nor ovarian cancer, these data do not suggest that our system is more informative than BRCA1 and BRCA2 for these malignancies specifically." (PMID 39226245, 2024). "Fisher's exact test indicated a nonsignificant trend for BRCA1 expression and a history of ovarian cancer (P=0.12)." (PMID 39742378, 2024). "Although not statistically significant, the molecular response was more frequently observed in patients with clinical benefit versus not (66% vs. 25% and 69% vs. 40% in ovarian cancer and BRCA1/2 mutant subgroups, respectively)." (PMID 38544832, 2024). "Here, we sought to see whether there was a link between BRCA1- and MGMT-methylated breast and ovarian cancer and each patient’s family history of cancer." (PMID 38542081, 2024). "Loss of the remaining BRCA1/2 allele is observed in the vast majority but still not all hereditary BRCA1/2-driven breast and ovarian carcinomas." (PMID 38612902, 2024). "Unlike their restricted use in breast or ovarian cancers, where approval is limited to those with BRCA1/2 alterations, PARPis in mCRPC are applied across a broader spectrum of genetic aberrations." (PMID 38396858, 2024). "A phase III FZOCUS-2 trial demonstrated a significant improvement in PFS with the utility of fluzoparib for maintenance therapy in platinum-sensitive, relapsed ovarian cancer patients, regardless of BRCA1/2 status." (PMID 37588193, 2024). "In contrast to the activation of canonical Wnt signaling in ovarian cancer cells with functional BRCA1 and BRCA2, our results show that loss of BRCA1 leads to the activation of the noncanonical Wnt signaling pathway in response to Wnt3A." (PMID 39028933, 2024). "There were 1121 and 1275 female first-degree family members in BRCA1 and BRCA2 families, respectively, of whom 144 and 65 family members in BRCA1 families were diagnosed with breast and ovarian cancer, respectively, and the corresponding number in BRCA2 families were 152 and 19 (eTable 4)." (PMID 38333895, 2024). "Furthermore, 36% of the BRCA1-methylated patients and 34.5% of the MGMT-methylated patients had a family history of cancer, including breast and ovarian cancer." (PMID 38542081, 2024).